UGT3A2 (UDP glycosyltransferase family 3 member A2)
Description:
[Isoform 1]: Involved in biotransformation reactions in which lipophilic substrates are conjugated with sugars to increase water solubility and enhance excretion. Such reactions are of major importance in the elimination of potentially toxic xenobiotics and endogenous compounds. UGT3A2 catalyzes the addition of sugar residues from UDP-glucose and UDP-xylose to a broad range of acceptor substrates including 4-methylumbelliferone, 1-hydroxypyrene, bioflavones, and estrogens. It has negligible activity toward bile acids and androgens. To a lesser extent, is also able to use UDP-galactose but is inactive with UDP-glucuronic acid or UDP-N-acetylglucosamine as sugar donors. [Isoform 2]: Lacks UDP-glycosyltransferase activity.
Tractability: Antibody: UniProt predicts a signal peptide or a membrane-spanning region. PROTAC: ubiquitination databases record sites on it.
Gene: Protein-coding gene on chromosome 5 (36,031,828 to 36,071,358, reverse strand). Ensembl gene ENSG00000168671.
Subcellular location: Membrane
Subcellular location (Human Protein Atlas): Nucleoplasm; Cytosol; Golgi apparatus
Pathways (Reactome):
Drug ADME: Aspirin ADME
Metabolism: Glucuronidation
Gene Ontology:
Molecular function: glucuronosyltransferase activity; UDP-galactosyltransferase activity; UDP-glycosyltransferase activity; UDP-xylosyltransferase activity; flavanone 7-O-beta-glucosyltransferase activity; isoflavone 7-O-glucosyltransferase activity
Biological process: cellular response to genistein
Cellular component: UDP-N-acetylglucosamine transferase complex; membrane
Genetic constraint (gnomAD): Loss-of-function variants: 32 observed, 39.79 expected, observed/expected ratio (o/e) 0.8, 90% interval 0.61 to 1.08. The upper end of that interval is the gene's LOEUF score, 1.08, which puts it in group 4 of 6, group 1 being the genes least tolerant of losing a copy. Missense variants: 602 observed, 660.08 expected, observed/expected ratio (o/e) 0.91, 90% interval 0.85 to 0.98. Synonymous variants: 241 observed, 242.93 expected, observed/expected ratio (o/e) 0.99, 90% interval 0.89 to 1.1.
Homologues: Orthologues: chimpanzee UGT3A2 (99% identical), rabbit UGT3A2 (76% identical), dog UGT3A2 (74% identical), mouse Ugt3a2 (66% identical), mouse Ugt3a1 (66% identical), rat Ugt3a1 (57% identical), tropical clawed frog ugt3a2 (44% identical), Drosophila melanogaster Ugt35B1 (26% identical), Drosophila melanogaster Ugt37C1 (26% identical), Drosophila melanogaster Ugt49C1 (26% identical), Caenorhabditis elegans ugt-15 (25% identical), Drosophila melanogaster Ugt37C2 (25% identical), and 80 more. Paralogues in human: UGT3A1 (78% identical), UGT2A3 (32% identical), UGT2B4 (31% identical), UGT1A1 (31% identical), UGT2B10 (31% identical), UGT2A2 (31% identical), UGT8 (31% identical), UGT2B7 (30% identical), UGT2B15 (30% identical), UGT2B17 (30% identical), UGT2B28 (29% identical), UGT2B11 (29% identical), and 9 more.
Diseases named in the same sentence as UGT3A2 in open-access papers:
UGT3A2 is named in the same sentence as 8 diseases in open-access papers, as found by Europe PMC text mining. Sharing a sentence is not in itself a finding about the gene and the disease. The quoted sentences say what the papers report.
metastatic disease (2 papers, 2015 to 2023). "In contrast, seven other non-synonymous or frameshift mutations (in genes UGT3A2, PLCG1, OR10K1, COL9A1, MAGEA6, CNBD1 and LG14) were detected only in the metastatic tumor, indicating a selection and proliferative advantage of cells with the diverse genotype under sunitinib treatment." (PMID 26474454, 2015). "Based on our in silico analysis and Wes validation, we evaluated UGT3A2 protein expression in plasma-derived sEVs from EWS patients (both localized and metastatic disease) and age-matched healthy controls." (PMID 37122563, 2023).
fusariosis (1 paper, 2017). "Further, human orthologues of 4 genesenriched in neurons, namely tkr-3 (orthologue GPBAR1), ugt-8(orthologue UGT3A2), R05G6.5.1 (orthologue NME5), and srw-85(orthologue GPR142) might act as potential candidates to unravel the link betweenneuronal stress and fusariosis." (PMID 29152379, 2017).
hepatoma (1 paper, 2015). "By using a cutoff value of β > 0.5, we identified five DME genes (CYP1B1, CYP8B1, GSTM2, GSTP1, and UGT3A2) that were regulated by DNA methylation in hepatoma cells." (PMID 26421064, 2015). "Among these DME genes, the downregulation of CYP1B1, CYP8B1, GSTM2, GSTP1, UGT2B15, and UGT3A2 in hepatoma cells could be explained by DNA methylation status." (PMID 26421064, 2015).
rhabdomyosarcoma (1 paper, 2023). A rare aggressive malignant mesenchymal neoplasm arising from skeletal muscle. "Further, immunohistochemistry (IHC) for UGT3A2 expression in representative EWS and Rhabdomyosarcoma patient tissue sections reveals stronger staining in EWS samples." (PMID 37122563, 2023).
thymoma (1 paper, 2023). A neoplasm arising from the epithelial cells of the thymus. "An 11-gene signature, including UGT3A2, established based on the immune microenvironment can be employed for the prediction of the prognosis of thymoma patients." (PMID 36816364, 2023).
cancer (3 papers, 2021 to 2023). A tumor composed of atypical neoplastic, often pleomorphic cells that invade other tissues. "This pattern was distinct from that of UGT3A2, which was only highly expressed in cancers derived from the uterus and testis (TGTC, UCEC, UCS)." (PMID 34503303, 2021). "We observed that relative to other cancer types, protein expression of GPR64, UGT3A2 and AMER2 is typically enhanced in EWS cancer cells." (PMID 37122563, 2023).
tumor (2 papers, 2023 to 2024). "We analyzed tumor sections from 5 patients for each tumor type and calculated H-scores that indicated stronger expression of UGT3A2 in EWS samples compared to RMS." (PMID 37122563, 2023). "Clinical validation of UGT3A2 expression in patient tumor tissues and plasma derived sEV samples demonstrated its specificity to EWS, indicating its potential as a EWS biomarker." (PMID 37122563, 2023). "Hence, we further evaluated the potential of UGT3A2 as a biomarker in the clinical validation studies in patient tumor sections and plasma-derived sEV samples." (PMID 37122563, 2023).
UGT3A2 also shares sentences with these, for which no sentence is quoted: hepatoblastoma (1 paper).